TLR4 (toll like receptor 4)
Diseases named in the same sentence as TLR4 in open-access papers (continued):
Sharing a sentence is not in itself a finding about the gene and the disease.
dermatitis (9 papers, 2014 to 2026). An inflammatory process affecting the skin. "In conclusion, the EVEs decreased TPA-induced skin inflammation, which was associated with a decrease in the TLR4/NF-κB/NLRP3 inflammasome." (PMID 39684233, 2024). "However, the precise molecular mechanism underlying how the TLR4/NF-κB signaling pathway mediates skin inflammation in rosacea remains incompletely understood." (PMID 40378103, 2025). "TLR4, which is expressed in various skin cells such as keratinocytes and fibroblasts, as well as immune cells, increases chronic skin inflammation." (PMID 39684233, 2024). "The topical application of 12-O-tetradecanoylphorbol-13-acetate (TPA), which induces skin inflammation in animal models, increases TLR4, TNF, and various inflammatory cytokines." (PMID 39684233, 2024). "Our experimental results suggest that EVEs have the potential to reduce skin inflammation by inhibiting the TLR4/NF-κB/NLRP3 inflammasome pathway." (PMID 39684233, 2024). "Furthermore, the significant alleviation of skin inflammation and the reduced infiltration of inflammatory cells were observed in minocycline-treated rosacea-like mice subjected to TLR4 overexpression and PDTC administration." (PMID 40378103, 2025). "Therefore, it is speculated that the increased expression of TLR4 may be due to secondary bacterial infection induced by scratches during the progression of dermatitis." (PMID 40333872, 2025). "In this study, we found that EVEs decreased skin inflammation by reducing HMGB1 and S100A8 and decreasing TLR4 expression, which then inhibited pyroptosis." (PMID 39684233, 2024). "Additionally, the results highlight that LA can ameliorate rosacea-like dermatitis through dual inhibition of KLK5 and TLR4/NF-κB signaling, while correcting metabolic disturbances, especially in phenylalanine metabolism." (PMID 41668756, 2026). "We hypothesized that EVEs inhibit the TLR4/NF-κB/NLRP3 inflammasome, which decreases IL-1β, IL-18, and pyroptosis, thereby attenuating TPA-induced skin inflammation." (PMID 39684233, 2024). "Thus, we hypothesized that EVEs decrease skin inflammation by reducing HMGB1, S100A8, and the TLR4/NF-κB/NLRP3 inflammasome pathway, which eventually decreases TPA-induced skin inflammation." (PMID 39684233, 2024). "Thus, the increase in DAMPs associated with chronic inflammation due to dermatitis and high-fat diet intake, as well as elevated saturated fatty acids in the blood, may lead to immune system exhaustion and negative feedback autoinhibition, resulting in decreased TLR4 expression." (PMID 38203647, 2023).
fibromyalgia (9 papers, 2015 to 2025). A chronic disorder of unknown etiology characterized by pain, stiffness, and tenderness in the muscles of neck, shoulders, back, hips, arms, and legs. "This study provides evidence of how TLR4 and associated molecules participate in the brain regions of this murine fibromyalgia model." (PMID 37240805, 2023). "Our results indicate that PD-L1 injection can attenuate fibromyalgia in mice: nociceptive-associated TLR4 was increased in fibromyalgia mice and could be diminished by PD-L1 injection." (PMID 41008336, 2025). "In addition, EA attenuated the fibromyalgia-associated reactive transformation of microglia and astrocytes and the activation of the pain-related TLR4–MyD88–TRAF6 signaling pathway." (PMID 41007675, 2025). "The stimulation of TLR4 in whole blood is associated with elevated release of cytokines and chemokines in various pain syndromes, such as chronic fatigue syndrome, endometriosis, fibromyalgia, IBS, migraine, and low back pain." (PMID 40787071, 2025). "Low-dose naltrexone (LDN), a recently employed treatment for fibromyalgia due to its ability to reduce glial inflammatory response and upregulate opioid signaling by regulating Toll-like receptor 4 (TLR-4) and transient opioid receptor blockade." (PMID 40337423, 2025). "In the current study, we examined the effects of glial inflammatory transformation, CB1 activity, and TLR4 signaling on fibromyalgia-like pain and the efficacy of EA treatment in an intermittent cold stress (ICS) mouse model." (PMID 41007675, 2025). "Our findings showed that EA and PD-L1 injection can mitigate mice fibromyalgia by decreasing TLR4 and downstream molecules such as MyD88, TRAF6, and pNF-κB." (PMID 41008336, 2025). "The TLR4 and MyD88 levels increased upon fibromyalgia induction (Tukey’s test, * p < 0.05, n = 6), which was attenuated by the EA treatment and PD-L1 injection (Tukey’s test, # p < 0.05, n = 6)." (PMID 41008336, 2025). "TLR4 has been suggested to play a significant role in the development of nociplastic pain syndromes, such as fibromyalgia, stress‐induced, and sleep deprivation‐induced pain." (PMID 40787071, 2025). "A recent article reported that eicosapentaenoic acid can reduce fibromyalgia nociception by moderating microglia/astrocytes and Toll-like receptor 4 in the mice cerebellum 5–7 (CB5-7)." (PMID 41008336, 2025). "Increased glial activity in nociplastic pain is a potential mechanism by which TLR4 antagonists (like naltrexone) relieve pain in fibromyalgia, although regulation of endogenous opioidergic tone is also a plausible hypothesis." (PMID 40787071, 2025). "In addition, the increased TLR4 and MyD88 concentrations in the SSCs of the fibromyalgia mice (Tukey’s test, * p < 0.05, n = 6) were inhibited by 2 Hz EA or PD-L1 injection (Tukey’s test, # p < 0.05, n = 6)." (PMID 41008336, 2025). "Furthermore, augmented levels of TLR4-MyD88-TRAF6 were detected in the thalamus of the fibromyalgia mice (* p < 0.05, n = 6), which decreased with the 2 Hz EA and PD-L1 (Tukey’s test, # p < 0.05, n = 6)." (PMID 41008336, 2025). "TLR4 was amplified in the fibromyalgia mice’s DRGs (Tukey’s test, * p < 0.05, n = 6)." (PMID 41008336, 2025). "Regarding TLR4 cascades, our results indicated comparable changes in the TLR4, MyD88, and TRAF6 protein concentrations in the fibromyalgia mice with those in the normal mice (Tukey’s test, * p < 0.05, n = 6)." (PMID 41008336, 2025). "We found an association between PD-L1/PD-1 present on microglia/astrocytes and TLR4 and its allied signaling pathways in a mouse model of intermittent cold stress (ICS)-induced fibromyalgia pain." (PMID 41008336, 2025). "The current study revealed that the suppression of fibromyalgia-like pain in a mouse model via EA requires the activation of the CB1–TLR4 signaling pathway, the mitigation of glial activation, and the suppression of the TLR4–MyD88–TRAF6 signaling pathway." (PMID 41007675, 2025).
fibromyalgia (continued). "In addition, fibromyalgia patients displayed lower concentrations of IFN-γ, IL-12, and IL-17A compared with the healthy controls, consistent with immunoreactions induced via TLR4 signaling." (PMID 41007675, 2025). "Indeed, the activation of TLR4 and TRL7 has been shown to enhance the activity of TRPV1 and TRPA1 channels, respectively, thereby facilitating neuronal excitability in individuals with fibromyalgia." (PMID 40787071, 2025). "LDN has been demonstrated to block TLR-4 in macrophages and microglia, inhibit or reduce T-cell proliferation and increase phagocytic activity of macrophages by raising IL-2 and TNF-α concentration and is therefore considered effective in chronic inflammatory disorders like fibromyalgia." (PMID 40337423, 2025). "It was also reported that the activation of TLR4 by lysozyme induced TRIF but not MyD88 and further triggered weak inflammatory cytokine expression and augmented glutamate release, suggesting the existence of a MyD88-independent pathway for nociceptive progression in fibromyalgia." (PMID 41007675, 2025).
gingivitis (9 papers, 2018 to 2025). A disorder involving inflammation of the gums; may affect surrounding and supporting structures of the teeth. "In particular, according to the reported studies, genetic polymorphisms of VDR TaqI (rs731236), CD14 −260C/T, IL10-592-C, IL-1Ra, and TLR4-299-G were associated with higher risk of developing gingivitis." (PMID 41300760, 2025). "In comparison, gingivitis biofilm activated fewer genes (e.g., TLR4) and cariogenic biofilm suppressed CD14, IRAK4, and IRF3 transcription." (PMID 31448244, 2019). "On the other hand, the TLR-4 mRNA was significantly higher in the SEC from the UWS of the gingivitis and the CP cohort as compared to that in SEC from the healthy saliva samples." (PMID 30571680, 2018). "In gingivitis saliva, lower concentrations of sTLR-4 correlated with lower TLR-4 mRNA levels in the paired SEC (r2 = 0.4)." (PMID 30571680, 2018). "Additionally, the LPS content is elevated in gingivitis sites compared to healthy sites, as determined by both TLR4-based and Limulus amebocyte lysate (LAL) methods." (PMID 39770870, 2024). "Furthermore, the direct correlation between the higher sTLR-4 and greater SECs TLR4 mRNA in gingivitis saliva perhaps support the sentinel functions of TLR4." (PMID 30571680, 2018). "In brief, all three types of biofilm strongly up-regulated TLR2 mRNA expression; TLR7 was significantly activated by commensal and gingivitis biofilms; TLR4 expression was only clearly increased by gingivitis biofilm; TLRs 3, 5, and 6 were not significantly affected by the biofilms." (PMID 31448244, 2019).
hemorrhagic stroke (9 papers, 2016 to 2025). A stroke caused by a bleed on the brain. "For cases of hemorrhagic stroke, polymorphisms in collagen genes, TLR4 and CD14 and even the gene that gives rise to C-reactive protein were identified." (PMID 38478535, 2024). "Antibodies can provide a more specific means of inhibiting TLR2 and 4; indeed, MTS510, a monoclonal antibody, has already been used to inhibit TLR4 expression in ischemic and hemorrhagic stroke in preclinical models." (PMID 34576137, 2021). "TLR4 in the thalamus can be activated in response to haemorrhagic stroke, but its specific role in CPSP is unclear." (PMID 34643849, 2021). "Neuroinflammation in post-SAH neuronal damage may be involved, given that heme and methemoglobin can act as toll-like receptor 4 (TLR4) agonists, as our lab and others have shown in hemorrhagic stroke." (PMID 35778649, 2022). "Therefore, microglial TLR4 might be a potential target for injury after hemorrhagic stroke." (PMID 35778649, 2022). "Further studies have suggested that targeting TLR4 exerted a neuroprotective role in resisting ICH-induced brain injury by impeding the Prx1/TLR4/NFκB signaling axis at 3 days after ICH, providing a promising anti-neuroinflammatory approach for hemorrhagic stroke." (PMID 36304999, 2022).
intestinal infection (9 papers, 2008 to 2025). "Hyaluronic acid was used for targeting ciprofloxacin SNEDDS against Salmonella typhi due to its ability to bind to CD44 and Toll-like receptor 4 (TLR4), which are overly expressed in intestinal infections." (PMID 39861711, 2025). "TLR4 can recognize and respond to LPS, and its downstream pathways dominate the microbiota-gut-brain axis when gastrointestinal infections or systemic bacterial infections occur." (PMID 38849869, 2024). "It has been confirmed that TLR4 is closely related to acute intestinal injury and intestinal infection." (PMID 32915230, 2020). "However, it is becoming clear that TLR4 overstimulation by periodic intestinal infections, or its understimulation following excessive use of antibiotics have the potential to affect the balance between ENS-microbial-derived products early in life setting the basis for developing GFD in adulthood." (PMID 28642706, 2017). "In addition, it should be noted that the expression of mediators of the TLR4 pathway in the large intestine and small intestine showed a consistent increase 12 h after the intravenous injection of LPS, which provides an important experimental basis for the study of new intestinal infection drugs." (PMID 31446815, 2019). "Physiological relevance of TLR4 signaling interference by HCV may relate to liver and intestine infection." (PMID 18509450, 2008).
Lewis lung carcinoma (9 papers, 2017 to 2022). "The Hsp70/90—TLR4—p38β MAPK—p300—C/EBPβ signaling pathway is activated in diverse types of murine cancer models including Lewis lung carcinoma, Apcmin/+ mice bearing intestinal adenocarcinoma and nude mice bearing human AsPC-1 pancreatic ductal adenocarcinoma." (PMID 34950660, 2021). "Orally administered 200 mg/kg SYQP induced obvious tumor regression, spleen weight increase, and the upregulation of the mRNA expression of TLR4-related cytokines in Lewis lung carcinoma–bearing mice." (PMID 33841142, 2021). "To investigate whether and how trained immunity was formed during cancer development, we established a subcutaneous Lewis lung carcinoma (LLC) model in mice that were devoid of TLR4, the prototypic pattern-recognition receptor for both pathogen and damage-associated signals." (PMID 36542153, 2022). "Here, we show that Toll-like receptor 4 (TLR4) mediates cancer-induced muscle wasting by directly activating muscle catabolism as well as stimulating an innate immune response in mice bearing Lewis lung carcinoma (LLC), and targeting TLR4 alone effectively abrogate muscle wasting." (PMID 28536426, 2017).
mucositis (9 papers, 2014 to 2025). Mucositis is inflammation and damage of the mucous membranes lining the mouth and other parts of the gastrointestinal (GI) tract. "However, it is important to note that contradictory findings have been observed, with TLR4 knockout C57BL6 mice more susceptible to mucositis induced by the same chemotherapeutic agent, irinotecan." (PMID 39080025, 2024). "It should be emphasized that aberrant TLR-4 expression may play an important role in the loss of tolerance to the enteric bacteria during chemotherapy-induced mucositis." (PMID 24742067, 2014). "Of interest, Wardill and colleagues showed that TLR4 knockout BALB/c mice were less likely to develop severe mucositis and diarrhea after irinotecan treatment, possibly due to the absence of an IL-6 response." (PMID 39080025, 2024). "The ability to model inflammation in single cell lines is limited, thus we adapted a colonic explant model to further examine TLR4 signalling in mucositis development." (PMID 35867263, 2023). "This work indicates that specific epithelial inhibition of TLR4 with these compounds is insufficient to manage mucositis-related inflammation." (PMID 35867263, 2023). "Previous study has shown that the genetic deletion of TLR4 renders mice resistant to chemotherapy-induced mucositis." (PMID 35867263, 2023). "The objective of this study was to determine the effects of glutamine (GLN) on TLR-4 signaling in intestinal mucosa during methotrexate (MTX)-induced mucositis in a rat." (PMID 24742067, 2014). "In conclusion, treatment with glutamine was associated with up-regulation of TLR-4 and MyD88 expression and a concomitant decrease in intestinal mucosal injury caused by MTX-induced mucositis in a rat." (PMID 24742067, 2014). "Of note, TLR4 is expressed on the basolateral surface of enterocytes and is only activated if LPS can translocate across the mucosal barrier, i.e., in the context of mucositis." (PMID 39080025, 2024). "We hypothesized in the present study that this TLR4 signaling is involved during MTX-induced mucositis and that glutamine could prevent intestinal mucosal injury or/and improve intestinal recovery by affecting this pathway." (PMID 24742067, 2014). "Which may be why TLR4 knockout models of mice are so effective at preventing mucositis." (PMID 35867263, 2023). "TLR4 antagonism using specific inhibitors TAK-242 and IAXO-102 was not effective at blocking IM in these pre-clinical models of mucositis." (PMID 35867263, 2023). "Since TLR4-MyD88/Mal-NF-kB signaling axis plays an important role in gut barrier function, further experiments are required to understand crosstalk between TLR-signaling and NF-kB-signaling during chemotherapy-induced mucositis." (PMID 24742067, 2014).
neutropenia (9 papers, 2011 to 2025). A decrease in the number of neutrophils found in the blood. "A previous study reported that TLR4 sequence variants (rs10759931, rs11536889, rs6478317, and rs1927911) increased the risk of neutropenia in children treated for ALL." (PMID 33339376, 2020). "It was previously reported that IP injection of LPS rapidly causes neutropenia and TLR4-dependent neutrophil accumulation in the lungs." (PMID 25184228, 2014). "After multivariate adjustment for GVHD, CMV serostatus and neutropenia, only the association between the TLR4 1063A>G and IFNG 874T>A combination and IA remained statistically significant (p = 0.044)." (PMID 21483748, 2011). "In contrast, a recent pre-clinical report of Lacticaseibacillus casei treatment reducing both 5-FU-induced leukopenia and TLR4 gene expression in the jejunum may explain why carriers of WT alleles of TLR4 rs4986790 had a decreased probability of neutropenia." (PMID 37162533, 2023). "TLR4 polymorphisms together with TLR2/Dectin-1 SNPs may also be important for the function of remaining immunocompetent cells during severe chemotherapy-induced neutropenia." (PMID 35163998, 2022). "Some polymorphisms, including TLR4 and CASP5, have been associated with a decreased probability of developing neutropenia." (PMID 40227705, 2025). "Sequence variants in the TLR4 have been associated with an increased risk of sepsis, Gram-negative BSI, as well as the development of chemotherapy-induced neutropenia." (PMID 33339376, 2020). "TLR2 and TLR4 mRNA expression was higher in patients with neutropenic fever than in the group with asymptomatic neutropenia after chemotherapy, although the difference was not statistically significant." (PMID 25412934, 2014).
normal tension glaucoma (9 papers, 2009 to 2025). "Recently a Japanese study using candidate gene methods found multiple SNPs in the toll-like receptor 4 (TLR4) gene associated with the risk of normal tension glaucoma (NTG), with an allelic P value of 0.0041 in the most highly associated SNP, rs7037117." (PMID 22761751, 2012). "To this end, we have evaluated the association of TLR4 polymorphisms with normal tension glaucoma and further investigated the phenotype-genotype correlation." (PMID 21921986, 2011). "Interestingly, recent studies in humans have also identified an association between TLR4 polymorphisms and normal tension glaucoma." (PMID 25180891, 2014). "Thus, further studies need to be replicated repeatedly to confirm the association of TLR4 SNPs and normal tension glaucoma." (PMID 21921986, 2011). "Previously, we analyzed the same SNPs in TLR4 that were examined in this study to determine whether they were associated with susceptibility to Behçet's disease (BD) and normal tension glaucoma." (PMID 20011079, 2009). "Moreover, while rs7037117 was associated with normal tension glaucoma in Japanese, our results suggest that TLR4 may also be implicated in high-tension POAG." (PMID 22773901, 2012). "Genetic variants of toll-like receptor 4, a transmembrane pathogen recognition receptor able to mediate the release of inflammatory cytokines, have been associated with POAG and normal-tension glaucoma in the Japanese population." (PMID 35101531, 2022). "We attempted to determine whether there were any associations between TLR4 polymorphisms and normal tension glaucoma in the South Korean population, and we further planned to investigate the phenotype-genotype correlation in NTG patients according to TLR4 SNPs." (PMID 21921986, 2011).